IL10 (interleukin 10)
Diseases named in the same sentence as IL10 in open-access papers (continued):
Sharing a sentence is not in itself a finding about the gene and the disease.
tumor (continued). "Probably directed in part by PGE2, based on reduced production of anti-tumor Th1 cytokines (TNFα, IFNγ and IL-2) and increased production of Th2 cytokines (IL-4, IL-10 and IL-6)." (PMID 19455240, 2007). "Cytokine releasechanged to an antiinflammatory, tumour-promoting pattern by increase in IL-4and IL-10 expression at the stage of CIN III." (PMID 18288269, 2007). "We evaluated a panel of basal cytokines more commonly involved in the tumor control and progression (IL-1 beta, IL-6, IL-8, IL-10, IL-12, TNF-α) both in 144 healthy donors and in 55 patients affected by MRCC treated with IL-2 based regimens." (PMID 17953739, 2007). "Preclinical studies show thattumor-induced inhibition of DC differentiation is mediated by tumor-derivedsoluble factors such as IL-10, IL-6, M-CSF, prostaglandins, and vascular endothelialgrowth factor (VEGF)." (PMID 18320010, 2007). "Gene therapy studies, however, have demonstrated IL-10-mediated inhibition of tumour growth and metastases with the outcome appearing dependent upon host immune competency and levels of IL-10 expression." (PMID 16641913, 2006). "Tumour volume was weakly correlated with C-reactive protein (r2=0.20, P=0.002), interleukin-6 (r2=0.20, P=0.002) and interleukin-10 (r2=0.24, P=0.001)." (PMID 17003778, 2006). "Tumour volume was correlated with C-reactive protein (r2=0.20, P=0.002), interleukin-6 (r2=0.20, P=0.002) and interleukin-10 (r2=0.24, P=0.001)." (PMID 17003778, 2006). "Our findings on blood DCs confirm previous studies on in vitro generated monocyte-derived DCs wherein tumor products (IL-10, prostanoids, gangliosides or ceramides) induced marked levels of apoptosis." (PMID 16417648, 2006). "Interleukin-10 levels had a positive correlation with tumour proliferation (ρ=0.452, P=0.05) and apoptosis (ρ=0.587, P=0.01)." (PMID 16641913, 2006). "Interleukin-10 is believed to contribute to tumour development by suppressing the antitumour immune responses." (PMID 16641913, 2006). "High VEGF, IL-6, IL-10, TGFβ and M-CSF levels in the tumour microenvironment block dendritic cell differentiation and maturation." (PMID 16832418, 2006). "Tumour proliferation and apoptosis correlate to progressive suppression of the CMI-associated cytokine TNF-α and to and higher levels of IL-10." (PMID 16641913, 2006). "Milk fermented by this LAB induced not only a decrease of IL-6, but also an increase of regulatory cytokines, principally IL-10, and also induced cell apoptosis in the tumour." (PMID 15987453, 2005). "Such tumour-produced molecules, including IL-4, IL-6, IL-10, CSF-1, TGFβ and prostaglandin E2 (PGE2), and TAM-produced factors such as IL-10 and PGE2, contribute to the general immunosuppression of the host as well as the antitumour activity of macrophages." (PMID 15164120, 2004). "A number of tumour-derived factors with the capacity of altering the maturation of CD34+or CD14+precursors, including VEGF, TGF-β, IL-10 and PGE2, have been excluded to be implicated in this pathway." (PMID 14562018, 2003). "To investigate the possible role of some tumour-related immunoactive soluble factors, we measured the plasmatic levels of vascular endothelial growth factor, IL-10 and spermine." (PMID 14562018, 2003). "The IL10 staining intensity was low in all tumours and these cells were within the stroma around the ducts in well to moderately differentiated tissues." (PMID 11870535, 2002). "CD8 KO mice displayed a spontaneous production of interleukin (IL)-4 and IL-10 locally in the tumour." (PMID 10496366, 1999). "The high level of IL-10 was demonstrated to inhibit Fab–SEA tumour therapy, since the therapeutic efficacy was significantly higher in IL-10 KO mice." (PMID 10496366, 1999). "Gene therapy protocols using tumour cells as a vaccine have to consider the adverse effects of IL-10." (PMID 9652756, 1998).
tumor (continued). "CD8+ Tc cells against the immunogenic IL-10-producing BALB/c plasmacytoma ADJ-PC-5 can be easily induced by immunization of BALB/c mice with X-irradiated ADJ-PC-5 tumor cells in vivo and in vitro." (PMID 9814607, 1998). "Collectively, nutrient competition (glucose, glutamine, arginine, methionine, tryptophan), secretion of suppressive metabolites (lactate, Kyn, adenosine), cytokine signaling (TGF-β, IL-10), and metabolic symbiosis between tumor cells and TAMs create a resilient immunosuppressive niche." (PMID 41601669, 2026). "The IL‐10 was the unique cytokine, which tends to increase oppositely to the length of the tumor." (PMID 41147460, 2026). "Moreover, GM-CSF, IFN-β, IL-10, IL-17, IL-12p70 and IL-23 levels in the serum were elevated in tumor-bearing mice that were given UBSC039; nonetheless, the IFN-γ level decreased." (PMID 41530841, 2026). "These immunosuppressive populations exerted their inhibitory effects through the secretion of potent immunosuppressive cytokines, including transforming growth factor-beta (TGF-β) and interleukin-10 (IL-10), thereby creating an immunologically privileged niche for tumor progression." (PMID 41496203, 2026). "For instance, butyrate can stimulate regulatory B cells to increase IL-10 expression via the aryl hydrocarbon receptor, driving somatic hypermutation and unbalanced IgA production that may facilitate tumor growth." (PMID 41486167, 2026). "Patient‐specific analysis of amplitude and duration of cytokine and chemokine persistence in CSF of humans after SCI revealed that proinflammatory chemokines CXCL1 and CCL3 tend to positively correlate with length of tumor, whereas anti‐inflammatory cytokine IL‐10 correlates negatively." (PMID 41147460, 2026). "IL-10 is an anti-inflammatory cytokine that can inhibit effective anti-tumor immune responses." (PMID 41607541, 2026). "This activation promotes IL-10 production, which subsequently drives tumor progression." (PMID 41614936, 2026). "However, within the tumor microenvironment, Tregs promote tumor immune evasion by suppressing the body's immune response through the secretion of cytokines such as IL‐10 and TGF‐β." (PMID 41560416, 2026). "Candida albicans may enable tumor cells to evade immune surveillance by promoting the production of IL-10." (PMID 41607541, 2026). "Furthermore, immunosuppressive factors in the TME, such as TGF‐β and IL‐10, further restrict NK cell activity and promote tumor immune escape." (PMID 41583906, 2026). "IL-10 expression reflected tumor progression and immune modulation." (PMID 41745410, 2026). "Notably, TAMs with an anti-inflammatory and pro-tumor M2 phenotype predominantly secrete immunosuppressive cytokines, such as IL-10 and transforming growth factor-beta (TGF-β), thereby promoting tumor proliferation and metastasis." (PMID 41328341, 2026). "Similarly, prostaglandin E2 (PGE2) released by tumor cells acts to suppress IL-12 and promotes IL-10 production in macrophages, further reinforcing the M2-like state." (PMID 41597210, 2026). "ELISA was performed to measure secretion of IL4, IL10, and TGFβ by tumor cells." (PMID 42094010, 2026). "Moreover, regulatory T-cells (Tregs), myeloid-derived suppressor cells (MDSCs), and immunosuppressive cytokines, such as transforming growth factor-beta (TGF-β) and interleukin-10 (IL-10), predominate within the tumor, further hampering anti-tumor immunity." (PMID 40700298, 2025). "Within the tumour microenvironment (TME), IL-35 and IL-10 work synergistically to drive T cell exhaustion by regulating inhibitory receptor expression and shaping exhaustion-associated transcriptomic profiles of CD8+ tumour-infiltrating lymphocytes (TILs)." (PMID 40416985, 2025). "Moreover, tumor cells can produce cytokines such as TGF-β, IL-10 or IL-6, that can contribute to immune suppression and tumor progression through the inhibition of T cell activity and the promotion of the differentiation of Tregs." (PMID 40805123, 2025).
tumor (continued). "In addition, the presence of MSCs in the tumor microenvironment determines the increase in the concentration of IL-6 and IL-10." (PMID 40573308, 2025). "At the same time, in the RLS40 model, DNase treatment resulted in a decrease in the mRNA levels of pro-tumor phenotype markers (Ccl17, Il10) and an increase in the mRNA levels of anti-tumor phenotype markers (Icam1, Tnfa, Vegfr1), as well as cell mobilization genes (Ern1, Stat3)." (PMID 40867260, 2025). "Additionally, M2-polarized TAMs secrete matrix-remodeling enzymes such as MMP-2, which facilitate tumor dissemination, while their production of IL-10 suppresses pro-inflammatory cytokines (TNF-α, IL-12, IL-1) and promotes tumor immune escape." (PMID 41394845, 2025). "In our study, the elevated IL-10 expression may reflect an adaptive immune response attempting to balance pro-inflammatory and anti-inflammatory signals in the presence of tumor antigens." (PMID 39931062, 2025). "To further verify the function of CAL-101 and whether IL-27 induces IL-10 expression, we detected the viral copy number and cytokine levels in the blood and tumor tissues at 8 and 72 hours after intravenous injection to the DT6606 subcutaneous tumor model." (PMID 40350204, 2025). "Our group and others have discovered that within the natural sequence of non-mutated tumor-associated antigens are MHCII-restricted epitopes that selectively generate either an IFN-γ or an IL-10 immune response." (PMID 40432134, 2025). "High levels of CCR2, CCR5, and CXCR4 at 1 week further supported active DC trafficking toward lymphoid tissues and tumor sites, while increased IL-10 may reflect early regulatory feedback within an immunostimulatory context." (PMID 41278869, 2025). "Remarkably, CPD-L1 plus AZA combination therapy could significantly upregulate the levels of IFN-γ, IL-12p70, TNF-α, and downregulate the levels of IL-6, IL-10 in tumor tissues." (PMID 40994623, 2025). "Furthermore, GBM recruits Tregs, which accumulate disproportionately in the tumor, produce IL-10, and sequester other cytokines to dampen cytotoxic T cell activity." (PMID 41583439, 2025). "Tregs, MDSCs, and tumor-associated macrophages (TAMs) collectively create an environment that inhibits iNKT cell function through mechanisms such as cytokine secretion (e.g., TGF-β, IL-10), metabolic competition, and immune checkpoint signaling." (PMID 39941775, 2025). "Here, bone marrow cells isolated from C57BL/6J mice were differentiated using macrophage colony stimulating factor into macrophages (M0) before polarization toward an M2-like, TCM phenotype by supplementation with interleukin (IL)-4, IL-10, and B16-F10 tumor-conditioned media." (PMID 41050935, 2025). "This suggests that IL-10 might facilitate metastatic processes, possibly by allowing tumor cells to escape immune surveillance in the lymphatic system." (PMID 41007766, 2025). "Moreover, IL-10 stimulates the expression of PD-L1 on tumor cells, thereby inhibiting T cells and NK cells through the activation of the PD-1/PD-L1 immune checkpoint signaling pathway." (PMID 40484866, 2025). "Moreover, the tumor microenvironment (TME) is also highly immunosuppressive, with tumor cells secreting IL-10 and TGF-β impairing the activity of both dendritic cells (DCs) and T cells." (PMID 40008881, 2025). "cSCC, UV-driven and highly mutagenic, is immunogenic yet exploits adaptive resistance: IFN-γ–induced PD-L1 upregulation on tumor and myeloid cells attenuates antitumor T-cell activity, reinforced by Tregs, IL-10/TGF-β, M2 macrophages, and impaired type I IFN signaling." (PMID 41463022, 2025). "Blocking C3a and C5a signaling restored IL-10 production and suppressed tumor growth." (PMID 41300283, 2025). "Conversely, interventions targeting IL-10 could be prioritized for patients in the early stages of HCC to limit tumor-induced immunosuppression." (PMID 41379186, 2025).
tumor (continued). "One study has reported that it can reduce IL-10 and IL-6 levels, which may help limit tumor growth and spread." (PMID 40160316, 2025). "Studies have shown that the inhibition of Treg infiltration or the blocking of their key molecular products (e.g., CTLA-4 or IL-10) significantly enhances DC-mediated anti-tumor immune responses, confirming the suppressive effect of Tregs on DCs’ antigen-presenting capacity in TME." (PMID 40432108, 2025). "This ratio may better reflect the immunosuppressive tumor microenvironment than absolute cytokine levels alone, as the anti-inflammatory effects of IL-10 may dominate when disproportionately elevated relative to IL-6." (PMID 40881684, 2025). "Due to tumor heterogeneity and other factors, the predictive power of a single IL-10 indicator may be limited, and it is necessary to combine other immune factors for a comprehensive assessment." (PMID 41438510, 2025). "On the other hand, they may also facilitate immune evasion, suppressing effective anti-tumor responses through the recruitment of immunosuppressive cells, such as regulatory T cells (Tregs), or by producing immunosuppressive cytokines like IL-10 and TGF-β." (PMID 40486595, 2025). "Additionally, mast cells can promote tumor progression by releasing anti-inflammatory cytokines such as IL-10 and TGF-β, which suppress immune responses." (PMID 40438115, 2025). "Pdgfc promotes angiogenesis and Il10 contributes to tumor immune evasion, suggesting that these factors might contribute to the enhanced progression of Mir34aΔMye CACs." (PMID 39425000, 2025). "Serum IL-10 levels have previously been shown to reflect systemic tumor burden." (PMID 40881684, 2025). "In this study, we demonstrated that our LNPs not only prolong the blood half‐life of the cytokine IL‐10, but also enrich IL‐10 in tumor tissues which is essential for improving the efficacy of adoptive T cell therapy as well as immune checkpoint blockade drugs." (PMID 40056044, 2025). "Additionally, γδ T cells usually produce higher amounts of anti-tumor cytokines (such as TNF and IFN-γ) than pro-tumor cytokines (for instance: IL-4, IL-10, IL-17, IL-22, and IL-35) within the TME, reflecting their prognostic value in cancer patients." (PMID 40148988, 2025). "Interestingly, the 4T-1 model also showed increased IL-10 production in both experimental groups, with DCV2 + T + Tumor secreting significantly less IL-10 than DCV1 + T + Tumor." (PMID 40573908, 2025). "Recent studies have shown that SCFAs can enhance the proliferation and function of NK cells by promoting the release of NK-derived extracellular vesicles and reducing the levels of anti-inflammatory cytokine IL-10, suggesting that SCFAs can contribute the anti-tumor NK cell responses." (PMID 41169397, 2025). "However, as tumours progress, the local cytokine milieu shifts to favour anti-inflammatory cues, such as IL-10 and CSF1, driving the recruitment of monocytes and their subsequent differentiation into immunosuppressive TAMs." (PMID 40948757, 2025). "Additionally, IL-10 positively correlated with poorer Child-Pugh score (r = 0.187, p<0.05), and serum levels of tumor markers, including AFP (r = 0.208, p<0.05) and protein induced by vitamin K absence-II (PIVKA-II) (r = 0.227, p<0.05)." (PMID 40568585, 2025). "Furthermore, abundant IL-10 expression is accompanied by an increase in other inflammatory mediators and its expression worsens the outcomes of various cancers, suggesting that IL-10 can serve as a key regulator of tumor immunity." (PMID 39187677, 2025). "Conversely, recent studies have identified STING as a cytosolic sensor that, when activated in B cells, induces an immunosuppressive profile characterized by increased IL-10 and PD-L1 expression, thereby compromising NK cell function in the tumor microenvironment." (PMID 40861439, 2025).
tumor (continued). "Interestingly, in the CD4+ T‐cell subset, also the frequency of cells expressing the anti‐inflammatory cytokine IL‐10 was significantly higher in the three tumor layers compared with PB." (PMID 40498413, 2025). "In contrast, IL-10 has shown anti-tumor properties in specific contexts." (PMID 40868199, 2025). "Importantly, IL-10 and IL-6 can be produced from tumor macrophages spontaneously, while B7-H4 was also produced from macrophages in an autocrine manner in human ovarian cancer." (PMID 40895302, 2025). "Moreover, anti-inflammatory factors, including TGF-β, IL-10, IL-13, and Arg1 in tumor tissues were notably downregulated by sh-TBX21 injection." (PMID 41573646, 2025). "Furthermore, tumor microenvironment induces imDCs to secret suppressive factors like Il-10, Arg1, Ido1 and Ido2." (PMID 40730800, 2025). "High levels of IL-10 may promote the expansion of Tregs which suppress the immune response and contribute to immune tolerance towards tumor cells." (PMID 40484866, 2025). "Moreover, MDSCs enhance angiogenesis by releasing vascular endothelial growth factors and IL-10, thus facilitating tumor growth and invasion." (PMID 40452834, 2025). "Tumor cells secrete cytokines, such as CSF-1, which bind to macrophage surface receptors and regulate the expression of immunosuppressive genes, including IL-1, IL-8, IL-10, and CSF-1." (PMID 40260303, 2025). "Interestingly, overexpression of IL-10 or administration of pegylated IL-10 in preclinical models also inhibited tumour growth." (PMID 39780187, 2025). "B cells may present tumor antigens and produce tumor-specific antibodies, but certain regulatory B cells (Bregs) can secrete IL-10 and TGF-β, suppressing effector T cells." (PMID 40297580, 2025). "Furthermore, we isolated the peritumor- and tumor-infiltrating M2 macrophages, and found that M2 macrophages in peritumor secreted significantly higher of IL-10 and lower levels of IFN-g and TNF-α, compared with that in tumor using Multiplex assay." (PMID 40756343, 2025). "Tregs, tumor-associated macrophages, and myeloid-derived suppressor cells inhibit T-cell activity via PD-1/PD-L1 and CTLA-4/CD80/86 pathways, while OSCC cells release VEGF, TGFβ, IL-6, and IL-10 to suppress immunity." (PMID 40924302, 2025). "IL-10 is a very strong anti-inflammatory cytokine that anergizes macrophages and dendritic cells thereby reducing the ability of the immune system to detect and destroy tumor cells." (PMID 40309351, 2025). "Third, hyperactive WBCs can suppress the function of other immune cells, such as T cells and NK cells, through the secretion of inhibitory cytokines like IL-10 and transforming growth factor-beta, weakening the body’s anti-tumor immune response and allowing tumor cells to escape immune surveillance." (PMID 39960903, 2025). "In the tissues of colorectal cancer patients, studies have found that various inhibitory cytokines secreted by the tumor and its associated stromal cells (such as VEGF, IL-10, TGF-β, etc.)interfere with the normal maturation process of DCs, leading to impaired antigen-presenting function." (PMID 40333202, 2025). "It is hypothesized that IL-10 may help tumor cells evade immune surveillance and potentially promote tumor growth." (PMID 40115022, 2025). "Additionally, TAMs suppress anti-tumor T-cell responses, enabling immune evasion and tumor growth by secreting anti-inflammatory cytokines (IL-10, TGF-β, PGE2) and inhibiting T-cell activation through checkpoint pathways (PD-1, CTLA-4)." (PMID 40563575, 2025). "Similarly, β-glucans from G. lucidum (50–200 μg/mL) were shown to upregulate the M1 phenotype markers (e.g., IL-12, IFN-γ) in tumor-associated macrophages but reduce the M2 phenotype markers (e.g., TGF-β, IL-10) in the TME." (PMID 40733125, 2025). "Moreover, interleukin 8 (IL8) and interleukin 10 (IL10) produced by TAMs promote ITGβ8 transcription in tumor cells through spi‐1 protooncogene (SPI1)." (PMID 39535362, 2025).